HIF1A (hypoxia inducible factor 1 subunit alpha)
Diseases named in the same sentence as HIF1A in open-access papers (continued):
Sharing a sentence is not in itself a finding about the gene and the disease.
tumor (continued). "HIF-1α is a transcription factor that regulates oxygen homeostasis and is thought to be related with tumor progression, angiogenesis, metastasis, and resistance, which may be responsible for chemoresistance under hypoxia." (PMID 34356634, 2021). "In addition, the increased expression of HIF-1α can also directly upregulate VEGF and PD-L1, which are associated with tumor angiogenesis and immune escape, respectively." (PMID 34513829, 2021). "Consequently, HIF-1α appears to be overexpressed in many malignant tumor types, whereas in normal tissues, lower protein levels were observed." (PMID 33916948, 2021). "Moreover, tumor cells stabilize HIF-1α in PSCs by increasing ROS production to increase glycolysis, leading to the formation of a “pseudo-hypoxic” environment for PSCs." (PMID 33546284, 2021). "While some background EpCAM staining was detected in non-tumor-bearing (PyMT−) bone marrow, a significant decrease in the number of EpCAM+ cells was detected in the bone marrow from Hif1α−/− PyMT+ mice compared to Hif1αf/f PyMT+ mice when normalized to total tumor weight at end point." (PMID 34556788, 2021). "Furthermore, altered tumor metabolism and enzymes regulated by hypoxia factor 1a (HIF-1a) are vital for the process of tumor progression, angiogenesis and metastasis." (PMID 35012094, 2021). "Interestingly, the expression of CD31 in HIF‐1α KO fibroblasts tumours is similar to that in HIF‐1α MOCK fibroblasts." (PMID 33943003, 2021). "It has been demonstrated that ONBs reverse hypoxia and suppress HIF-1α activity in tumor cells." (PMID 33659251, 2021). "The Warburg effect induced by HIF-1α activation promotes cell proliferation and tumor growth." (PMID 34277453, 2021). "Studies have shown that tissue is upregulated by HIF-1a promoter steady-state reaction, to adapt to hypoxia, which may further facilitate tumor growth and tumor angiogenesis." (PMID 34521431, 2021). "The ubiquitin-mediated proteolysis could be related to autophagy activation, a process often involved in tumor response to radiation, although also HIF-1α promotes autophagic proteolysis of the Dicer complex and enhances tumor metastasis in GBM cells." (PMID 33923454, 2021). "In particular, the relationship between chronic or acute hypoxia and lung cancer tumor metastatic potential has specifically been investigated, revealing that acute hypoxia and concomitantly high HIF-1α stability most strongly increase tumor growth and metastasis." (PMID 34940617, 2021). "In the similar IHC studies in samples of urothelial carcinoma overexpression of COX-2 was associated with high expression level of HIF-1a and high amount of CD68+ TAMs that promoted tumor progression and angiogenesis through TAM infiltration and hypoxia in tumor sites." (PMID 34209679, 2021). "Notably, unlike gene activation analysis, we observed the emergence of some pure phenotypes, M2a, and M2c, tending to favor tumor progression when we knocked out HIF1-α." (PMID 34177892, 2021). "Targeting HIF-1α could be considered a therapeutic approach for both hypoxic and normoxic tumor cells." (PMID 35127467, 2021). "Reduced cytotoxic activity of CTLs against cancer cells could also stem from HIF-1α-driven decreased expression of MHC class I on the surface of tumor cells, as well as be associated with tumor-protective role of extracellular adenosine." (PMID 33918883, 2021). "In addition, the importance of HIF-1a in RCC is indicated by several reports demonstrating that positive immunohistochemical staining of HIF-1a correlates with higher grade tumor and poor prognosis." (PMID 34131104, 2021). "Our data demonstrate that the targeting of HIF-1α or its regulatory pathways acts at the tumor- and SC-level, and may be an appealing strategy to overcome the microenvironment-mediated protection of CLL cells." (PMID 34207596, 2021).
tumor (continued). "They demonstrated that in a coculture in vitro system, a loss of HIF-1α in macrophages derived from cd11b+ splenocytes did not impact the capacity to infiltrate tumor spheroids." (PMID 34831183, 2021). "In the tumor, under hypoxic conditions, HIF-1α expression and activity are regulated by NF-κB." (PMID 34360919, 2021). "As for the reason why the function of HIF-1α in ccRCC was identified as an oncogene or a tumor suppressor, we speculated that HIF-1α might play different roles at the beginning or advanced stage of ccRCC." (PMID 34926261, 2021). "HIF-1α takes part in tumor angiogenesis via the regulation of VEGF expression." (PMID 33467713, 2021). "Depletion of HIF1α in A549 cells rescued the expression of miR101 in tumor cells and exosomes." (PMID 34362882, 2021). "One potential mechanism to explain these results could be a probable decrease in prolyl hydroxylase enzyme 3 (PHD3), which together with the von Hippel-Lindau tumor suppressor participates in the proteasomal-degradation of HIF-1α." (PMID 33513753, 2021). "A clinical trial demonstrated that TPT can downregulate HIF-1α in solid advanced tumours." (PMID 35004308, 2021). "On the other hand, activation of HIF-1α is an important mechanism that mediates tumor progression." (PMID 33819917, 2021). "The results of our study support that targeting of APEX1/HIF-1α and disturbing its interaction may lead to the inhibition of LC tumor pH, migration, and angiogenesis." (PMID 33990544, 2021). "The roles of hypoxia and HIF-1α on tumor cell invasion and metastasis are well established." (PMID 34360919, 2021). "During hypoxic conditions, the higher glucose uptake by cancer cells could upregulate the stability of HIF-1α, which in turn leads to the attenuation of anti-tumor immune responses." (PMID 33532902, 2021). "In CLL, miR-92-1 targets VHL, a known tumour suppressor regulating HIF-1α." (PMID 34968247, 2021). "Additionally, lactate has been reported to stabilize HIF-1α, activate NF-κB signaling cascade, and also induce secretion of VEGF from tumor-associated stromal cells, all of which are the characteristics of mesenchymal GBM." (PMID 33762019, 2021). "Some tumor-suppressor microRNAs may increase the radiosensitivity of hypoxic tumors by inhibiting glycolysis in them via the downregulation of HIF-1α, as it was shown for miR-33a in melanoma cells." (PMID 33806538, 2021). "As ROS stabilizes hypoxia-inducible factor-1 alpha (HIF-1α) and promotes tumor progression, we determined if LDHA or LDHB knockout, which reduces oxidative stress, could also reduce HIF-1α protein level in tumors." (PMID 34176927, 2021). "In one study, the researcher declared that HIF-1α could be inhibited by zinc to improve the therapeutic effect of tumor." (PMID 34926261, 2021). "In addition, after TMZ treatment, the group with both HIF1α and HIF2α knockout had the lowest tumour weight and longest survival time among all groups." (PMID 33986256, 2021). "Notably, specific deletion of HIF-1α in NK cells impairs NK cell tumor cytotoxicity, indicating that HIF-1α is also essential for maintaining tumor immunosurveillance in NK cells, besides its function as a hypoxia-responsive transcription factor." (PMID 33920906, 2021). "Additionally, an in vivo study shows that in tumor cells, the levels of HIF-1α and HIF-2α are high on average but vary depending on the type of cells." (PMID 34639040, 2021). "Besides, the overexpression of HIF-1α is associated with the mutations of the several oncogenes (p54, PTEN, or VHL) and thus, HIF-1α overexpression significantly affects the tumour growth, metastasis, and invasion properties." (PMID 33206367, 2021). "Furthermore, the tumor inflammatory signaling, HIF-1α, p-NFκB, COX-2, and PD-L1 were significantly down-regulated by melatonin, HBO and combined treatments." (PMID 34671196, 2021). "Interestingly, HDAC1 was also found to be overexpressed in CRC58 and promoted tumor angiogenesis by activating HIF1α/VEGFA59." (PMID 34031358, 2021).
tumor (continued). "In tumor-associated macrophages (TAM), HIF-2α and HIF-1α levels are high." (PMID 34639040, 2021). "High expression of HIF-1α induces tumor cells to adapt to hypoxia and grow rapidly." (PMID 34404434, 2021). "VEGF and HIF1A were targeted and regulated by miR-578 in regulation of tumor progression." (PMID 33962616, 2021). "Both HIF1α and HIF2α regulate GBM growth initially, but with tumour development, the regulation of HIF2α decreases, while HIF1α becomes increasingly important; eventually, GBM development is regulated by only HIF1α1,2, suggesting that targeting HIF1α alone can inhibit GBM growth." (PMID 33762574, 2021). "The secretion of CCL5 from HIF‐1α high expressed fibroblasts might be combined with CCR5 to promote the growth of tumour cells." (PMID 33943003, 2021). "MO-460 is a moracin-derived product that generates and accumulates SGs under hypoxic circumstances by binding and inhibiting hnRNPA2B1 and reducing HIF-1α protein production.hnRNPA2B1 has been identified as a unique molecular target in hypoxia-induced tumor survival." (PMID 35004322, 2021). "Furthermore, the differentiation process of plasmacytoid DC (pDC) was also abolished by HIF-1α, which resulted in tumor progression." (PMID 33816483, 2021). "Moreover, since HIF-1α is activated by succinate, the use of HIF-1α inhibitors has been proposed as an alternative and effective strategy to block the tumor progression driven by succinate." (PMID 34065551, 2021). "Therefore, in the context of in vitro cell culture under normoxia and nutrient-rich conditions, HIF1A behaves as a strong tumor suppressor through cell-autonomous mechanisms." (PMID 33654095, 2021). "Furthermore, lncRNA GHET1 knockdown decreased HIF-1α expression in hypoxia and significantly inhibited tumor development in vivo." (PMID 33869194, 2021). "Importantly, some metabolites of the TCA cycle, such as succinate, fumarate, and α-ketoglutarate, act as “oncometabolites” that support tumor growth via oncogenic signaling, inter alia via upregulation and stabilization of HIF-1α." (PMID 34381722, 2021). "It is well known that the hypoxic tumor microenvironment results in hypoxia-induced transcription factors (HIF-1α, HIF-2α)-mediated production of locally produced chemokines/cytokines emanating from normal prostate epithelial cells, periprostatic adipocytes, and PCa cells." (PMID 34959723, 2021). "Therefore, the combination of DOX and CaO2-MNPs decreases HIF-1α protein expression in vivo and, thus, attenuates hypoxia responses to inhibit tumor growth in TNBC." (PMID 33546453, 2021). "Hence, we knocked out HIF1α, because this factor is affected by hypoxia, a constitutive condition in a tumor microenvironment, that triggers the M2 polarizing effect." (PMID 34177892, 2021). "However, CD73, a HIF-1α-regulatory molecule that is mainly expressed on Treg cells or some tumor cells, regulates extracellular adenosine production." (PMID 34737746, 2021). "Finally, TAM can be found in hypoxic parts of the tumor and it can express HIF-1α, which regulates the transcription of VEGF largely associated with angiogenesis." (PMID 33418996, 2021). "However, several miRNAs, such as miR-155, miR-21-5p, and miR-23-3p, can downregulate VHL tumor suppressors and consequently modify HIF-1α stability." (PMID 34575844, 2021). "In hypoxic microenvironments, tumor cells overproduce HIF-1α, which is conducive to survival." (PMID 34784907, 2021). "HIF1α is stabilized under hypoxic conditions and responsible for directing tumor angiogenesis." (PMID 34470658, 2021). "Both PD-L1 and HIF-1α play major roles in tumor immune evasion." (PMID 34680439, 2021).
tumor (continued). "By inducing glycolysis-related genes products such as hexokinase 2 (HK2), lactate dehydrogenase A (LDHA), and glucose transporter 1 (GLUT1, also known as solute carrier family A1, SLC2A1), HIF-1α switches the glucose metabolism of hypoxic tumor cells to the glycolytic pathway." (PMID 35096814, 2021). "Interestingly, AHR and HIF-1α share the dimerization partner ARNT/HIF1β, showing linked processes of tumor progression, metabolic pathways, and vascular development." (PMID 34572746, 2021). "In such a way, STAT3 and HIF-1α can mediate tumor immunity and immune evasion." (PMID 34692527, 2021). "Because of changes in oxygen, HIF-1a activates the transcription of over 100 downstream genes involved in controlling the metabolism of glucose, proliferation, cell migration, and angiogenesis to regulate vital biological processes required for tumor survival." (PMID 34162394, 2021). "Sema4D is induced by hypoxia through a HIF-1α-dependent mechanism in tumors from different origin such as colon, oral squamous cell and lung carcinoma, with consequent regulation of tumor vascularization." (PMID 33858502, 2021). "There is evidence that HIF-1α activity in CAFs can function as a tumor promoter." (PMID 34202979, 2021). "Notably, baicalein or TAM combined with baicalein decreased the HIF‐1α expression in tumour tissues." (PMID 34841716, 2021). "HIF-1α is considered to be a central promoter of tumor hypoxia adaptive response." (PMID 34093799, 2021). "Also, the HIF-1α expression of tumor cells was significantly higher in the stroma-high subgroup than in the stroma-low subgroup." (PMID 33810015, 2021). "To further validate the impact of the HIF-1α/HECTD2 axis on tumor growth in vivo, we established HIF-1α overexpression and/or HECTD2 knockdown models in 786-O cells and discovered that overexpressing HIF-1α increased tumor volume and weight (vs. the vector group)." (PMID 35004677, 2021). "Hypoxia-activated HIF-1α enhances lactate acidosis in the tumor microenvironment, and dysregulated pH in the tumor microenvironment activates SREBP-1c and FASN expression to speed up the fatty acid synthesis required for plasma membrane synthesis in rapidly proliferating cells." (PMID 34869321, 2021). "However, HIF1α is not a key regulator of NK cell metabolism and the data suggests that HIF1α expression in NK cells can have pro-tumour effects." (PMID 34090499, 2021). "Moreover, the levels of tumor metastasis-related molecules, HIF-1α expression, and LOX secretion were increased in RT-R-MDA-MB-231 tumor tissue compared to MDA-MB-231 tumor tissue and were even higher in CD24−/low/CD44+ tumor tissue." (PMID 34502547, 2021). "HIF-1α inhibits plasmacytoid DC (pDC) differentiation, leading to tumor progression." (PMID 35047016, 2021). "In addition, the anticancer strategy of statins combined with cytotoxic drugs in anoxic environments is valuable in melanoma, where these drugs neutralize the structural expression of HIF-1α in the tumor." (PMID 34858839, 2021). "For example, the HIF1α/ARNT complex promotes tumor angiogenesis, erythropoiesis and glycolysis." (PMID 33446631, 2021). "After tumor recurrence, the levels of HIF1A and immune-related genes started to increase." (PMID 34305618, 2021). "Based on the results of preclinical studies, future randomized clinical trials should be designed to evaluate vitamin C activity in specific tumor molecular subtypes, such as those characterized by HIF-1α over-expression and TET2, L2HGDH, IDH1/2, or WT1 altered pathways." (PMID 33804775, 2021). "HIF-1α is an important downstream target of miR-21 in regulating tumor angiogenesis." (PMID 35083006, 2021). "In addition, silencing mTORC1 and eIF4E upregulated Beclin-1 and LC3 and decreased the expression of HIF-1α, thereby inhibiting tumor cell proliferation." (PMID 34917504, 2021).
tumor (continued). "Furthermore, treatments with DDP and the HIF-1α inhibitor PX-478 in the human EC xenograft animal model confirmed that the tumor expression levels of the molecules in the lncRNA-EMS/miR-758-3p/WTAP axis were associated with tumor rejection efficiencies." (PMID 34081626, 2021). "Interestingly, HIF-1α activity increases following radiotherapy as a result of tumor reoxygenation and the formation of reactive oxygen species." (PMID 34746010, 2021). "In addition, compared with the other subtypes, the M2 subtype was more closely related to the activation of HIF-1A and the tumor hypoxic microenvironment." (PMID 33985530, 2021). "Therefore, one important consequence of hypoxia is the induction of HIF-1α, which activates a series of downstream genes that facilitate tumor cell survival in the hypoxia microenvironment, such as autophagy-related genes Beclin1." (PMID 34465721, 2021). "Moreover, deletion of PKM2 impaired proliferation, increased apoptosis, and decreased PDA tumor growth by negatively impacting both HIF-1α and VEGF secretion through the NF-kB/p65, mTOR and Akt/c-Myc pathways." (PMID 33804240, 2021). "As expected, HIF-1α immunoreactivity was detected in all cellular compartments of tumor cell." (PMID 34440169, 2021). "Digoxin inhibits HIF-1α protein synthesis, leading to a decrease in tumor growth in xenografts." (PMID 34200019, 2021). "Hypoxia characterization (pimonidazole, CA-IX and HIF-1α) was also performed in different preclinical NSCLC BM models induced either by intracerebral injection of tumor cells (H2030-Br3M, H1915) into the cortex and striatum, or intracardial injection of tumor cells (H2030-Br3M)." (PMID 34045576, 2021). "Activation of either the PI3K-Akt-mTOR or Ras-Raf-MEK-ERK signaling axis was shown to induce COX-2 expression in a variety of tumors; overexpression of COX-2 by HIF-1α induction further increased tumor cell proliferation, angiogenesis, drug resistance, and decreased apoptosis." (PMID 33805447, 2021). "By contrast, studies have shown that HIF-1α can upregulate EZH2 expression in tumor models." (PMID 34737746, 2021). "The role of HIF-1α in vivo was explored by tumor implantation in nude mice." (PMID 34926261, 2021). "Indeed, deletion of HIF1α in NK cells resulted in an improved ability to reduce tumor burden in two independent studies, which was attributed to a dysfunctional VEGF axis or increased effector functions through IL-18 signaling." (PMID 34396954, 2021). "Hence, exceeding this radius would likely form an area of hypoxia in the MTSs, which would lead to genetic and metabolic reprogramming regulated by hypoxic induction factor (HIF1A), enabling tumor cells to acquire a more aggressive phenotype." (PMID 38650282, 2021). "Excessive HIF-1α, which is produced due to hypoxia of tumor cells, might greatly contribute to the difficulty of tumor therapy." (PMID 34093799, 2021). "The data indicate that the bioactive SFN combined with AZ decreased intra-tumor hypoxia and the subsequent expression of HIF-1α and the downstream effector CAIX involved in in decreasing the level of intra-tumor hypoxia and the downstream effector CAIX involved in low oxygen BC xenografts." (PMID 34316328, 2021). "In addition, hypoxia inducible factor-1α (HIF-1α) is a key regulator in hypoxia inducing tumor growth." (PMID 35127500, 2021). "In addition, hypoxia mediates overexpression of the carbonic anhydrase IX (CA IX) gene in an HIF-1α-dependent manner which acts as a pH regulator in the tumor." (PMID 34639215, 2021). "We found that PCNA and Ki‐67 were abundant in HIF‐1α MOCK fibroblasts tumour tissues." (PMID 33943003, 2021).